FASN (fatty acid synthase)
Diseases named in the same sentence as FASN in open-access papers (continued):
Sharing a sentence is not in itself a finding about the gene and the disease.
cervical cancer (continued). "Moreover, we aimed to verify that the regulation of FASN in cervical cancer cells could affect the interaction between tumor cells and human lymphatic endothelial cells (HLECs)." (PMID 35597782, 2022). "Functional validation indicated that upregulated FASN and SPP1 contribute to malignant behaviors in cervical cancer cells." (PMID 42198359, 2026). "To further investigate the role of FOXK2 in regulating lipid metabolism in a cervical cancer mouse model, we assessed the expression levels of ACC1, FASN, and CPT1A in tumor tissues." (PMID 40641601, 2025). "Specifically, the genes ABL1, BAX, FASN, and PLAU exhibited abnormally high expression levels in cervical cancer specimens, in stark contrast to BCL2, IGF1, and NTRK3, which were markedly under-expressed." (PMID 38988712, 2024). "Indeed, abnormal cholesterol and lipid metabolism in tumor cells might facilitate LN metastasis, as observed for enhanced fatty acid synthase expression in cervical cancer and the adaptative switch of lipid metabolism to fatty acid oxidation, which has been found to be required for LN metastasis." (PMID 37573356, 2023). "Compared to the normal cervical samples, all cervical cancer lines, including HeLa, CaSki, C33A, MS751, HeLa229, ME180, and SiHa, showed higher expression of FASN at the mRNA and protein levels." (PMID 35597782, 2022). "FASN regulates cholesterol reprogramming, subsequently activating the lipid raft-related c-Src/AKT/FAK signaling pathway, which results in enhanced migration and invasion of cervical cancer cells." (PMID 40641601, 2025). "In cervical cancer cells, we utilized immunofluorescence experiments and discovered that the knockdown of FOXK2 led to a reduction in the expression level of CPT1A, whereas the expression levels of FASN and ACC1 increased." (PMID 40641601, 2025). "The results we presented demonstrated that enzymatic domains of FASN that were at the KS but not KR or TE were essential for inhibiting cholesterol reprogramming in cervical cancer cells." (PMID 35597782, 2022). "These and our results suggest that a combined FASN and MMP1 inhibition may be beneficial for cervical cancer patients." (PMID 30283446, 2018). "Consistently, although SIRT3 could enhance invasion and metastasis by improving the expression of FASN in cervical cancer, TCGA-based results did not reveal a correlation between high expression of FASN and poor outcome for UCEC." (PMID 34879004, 2021).
triple-negative breast carcinoma (24 papers, 2014 to 2026). An invasive breast carcinoma which is negative for expression of estrogen receptor (ER), progesterone receptor (PR), and human epidermal growth factor receptor 2 (HER2). "Overexpression of FASN was observed in 70% of patients with operable triple-negative breast cancer, which was linked to poor prognosis." (PMID 40002245, 2025). "For example, the expression of fatty acid synthase (FASN) in triple-negative breast cancer (TNBC) is upregulated, causing lipid accumulation, which is usually positively correlated with cisplatin resistance." (PMID 37004014, 2023). "ADP expression in carcinoma cells significantly correlates with lower FASN expression in triple-negative breast cancer and salivary duct carcinoma." (PMID 41008850, 2025). "Another study classified triple-negative breast cancer into three distinct metabolic phenotypes based on their specific metabolic profiles, among which lipid-synthesizing triple-negative breast cancer was relatively sensitive to FASN inhibitors." (PMID 40002245, 2025). "Based on these findings, the proton pump inhibitor omeprazole was repurposed to target FASN in a single-arm phase II trial for triple-negative breast cancer." (PMID 38467328, 2024). "Targeting FASN by repurposing proton pump inhibitors has generated impressive outcomes in triple-negative breast cancer patients." (PMID 38467328, 2024). "Here, we demonstrate that NFYAv1, a long-form variant, upregulates the transcription of essential lipogenic enzymes ACACA and FASN to enhance the malignant behavior of triple-negative breast cancer (TNBC)." (PMID 37268670, 2023). "Upregulated miR-193b expression results in reduced fatty acid synthase (FASN), which in turn makes triple-negative breast cancer cells more sensitive to the effects of metformin." (PMID 37510280, 2023). "Based on these current findings, an IGF-1-mTORC1-SRPK2 axis contributes to lipogenic metabolic regulation through FASN in triple negative breast cancer cells." (PMID 36096767, 2022). "In the present study, we report a potential IGF-1 induced metabolic programming of de novo fatty acid synthesis in triple negative breast cancer cells through FASN." (PMID 36096767, 2022). "Other studies proved the ability of G28 to inhibit FASN activity in triple-negative breast cancer (TNBC) cells." (PMID 32438613, 2020). "FASN has been reported to be significantly down-regulated and decrease of FASN protein level was observed following 24 hours of metformin treatment in triple negative breast cancer cells." (PMID 27791206, 2016). "We demonstrate that the fatty acid synthase inhibitor TVB-2640 synergizes with the topoisomerase inhibitor SN-38 in triple-negative breast cancer (TNBC) BM cell lines, upregulates FAS and downregulates cell cycle progression gene expression, and slows the motility of TNBC BM cell lines." (PMID 38858374, 2024). "Given that we observed this affect in three additional triple-negative breast cancer cell lines, these results demonstrate that this modulation of FASN and palmitate synthesis from this pathway could be subtype specific." (PMID 36096767, 2022). "One study has demonstrated that inhibition of FASN and EGFR increased the sensitivity to chemotherapy in triple-negative breast cancer." (PMID 39495391, 2024). "Restraining the expressions of FASN and ACC can limit the growth, proliferation, and metastasis of triple-negative breast cancer cells, and simultaneously inhibiting the expression of these two enzymes is far superior than restraining only one of them." (PMID 37120513, 2023). "In this study, we tested the effects of FASN and ACC inhibitors on triple-negative breast cancer MDA-MB-231 cells." (PMID 37120513, 2023). "Here, diesters G28, G37 and G56 and two G28 derivatives, monoesters M1 and M2, were synthesized and assessed in vitro for their cytotoxic, FASN inhibition and apoptotic activities in MDA-MB-231 triple-negative breast cancer (TNBC) cells." (PMID 29751678, 2018).
triple-negative breast carcinoma (continued). "According to further refined distinct subtypes, the distribution of LDHA and FASN expression showed an inverse correlation, with LDHA H-scores increasing from LumA to triple-negative breast cancer (TNBC) and, conversely, with FASN H-scores decreasing from LumA to TNBC." (PMID 32899149, 2020). "It has been recently reported that certain cancer cells such as aggressive triple-negative breast cancer cell lines express markers of lipolysis (lipoprotein lipase, LPL) and exogenous fatty acid uptake (CD36), concomitantly with markers of de novo lipogenesis (FASN)." (PMID 25215509, 2014).
breast tumors (23 papers, 2014 to 2025). "Genetic or pharmacological inhibition of fatty acid synthase reduces breast tumor growth in the brain, demonstrating that differences in nutrient availability across metastatic sites can result in targetable metabolic dependencies." (PMID 39998776, 2025). "To assess the relationship between FASN gene expression and immune status in breast tumors (TCGA BRCA), we inferred immune cell content by applying CIBERSORTx to the bulk RNA-seq profiles." (PMID 39349429, 2024). "It has been also observed to suppress the fatty acid synthase gene whose levels are usually increased in breast tumors." (PMID 35015763, 2022). "FASN mRNA expression was significantly higher in PR-positive breast tumors than in PR-negative tumors (p < 0.0001; n=1,700), as determined by PR gene expression profiles." (PMID 33335078, 2020). "Reclassification of HER2-positive breast tumors based on FASN gene expression predicted a significantly inferior relapse-free and distant metastasis-free survival in HER2+/FASN+ patients." (PMID 33194695, 2020). "Prior analyses have also illustrated that breast tumor expression of immuno-inflammatory markers and fatty acid synthase vary across established breast tumor subtypes." (PMID 32698885, 2020). "Fatty acid synthase (FASN) is over-expressed in some breast tumors and FASN inhibition limits breast tumor growth." (PMID 32111826, 2020). "HER-2-enriched FASN + breast tumors expressed LOX-1 four times more than luminal A tumours, and two times more than basal-like tumors." (PMID 30718451, 2019). "Treatment with a FASN inhibitor led to the arrest of cell growth and apoptosis of breast tumor cells, further reinforcing the role of FASN in tumorigenesis." (PMID 30717356, 2019). "In agreement with our results, the exclusion of the extrinsic apoptosis pathway was previously reported for breast tumor cells after FASN inhibition." (PMID 24964211, 2014). "Furthermore, genetic disruption of FASN expression improved the survival of mice with breast tumors implanted in the brain." (PMID 37124526, 2023). "In addition, the lipogenic enzyme fatty acid synthase (FASN) is required for EMT expansion in breast tumor." (PMID 35736645, 2022). "Therefore, FASN overexpression may contribute to the metastases of breast tumor in some specific location such as the brain, and thus have an adverse impact on the prognosis." (PMID 37124526, 2023). "Notably, FASN and ACL are upregulated in HR+ breast tumors, both have been shown to be essential for cancer cell viability and tumorigenesis and their increased expression in breast tumors is associated with poor prognosis." (PMID 34638293, 2021). "Consistent with the CIBERSORTx-based predictions, FASN expression was found to be negatively correlated with a signature of cytolytic activity (CYT) and HLA-I expression in breast tumors." (PMID 39349429, 2024). "Despite that associations between FASN expression and prognostic indices were not demonstrated in this study, the possibility cannot be excluded that FASN overexpression may have adverse impacts on the prognosis on breast tumors depending on the pathological subtype and location." (PMID 37124526, 2023). "Based on our previous in vitro data, an insufficient capacity for quenching excess ROS might be related to the lack of breast tumor development in FASN-negative regions in PyMT animals." (PMID 31676791, 2019). "However, FASN-negative regions did not develop breast tumors." (PMID 31676791, 2019). "Along the same lines, clinical breast tumor specimens appear to universally co-express LPL and FASN irrespective of their biomarker status." (PMID 25215509, 2014).
viral infection (22 papers, 2010 to 2025). "Viral infection has also been linked to changes in FASN expression, and inhibition of human FASN activity can attenuate the replication of at least 27 viruses from 15 different families." (PMID 40558086, 2025). "Numerous studies discuss and show promising results targets for NSAIDs, mTOR pathway regulators, and FASN inhibitors in viral infection associated cancers but additional in vivo studies need to be done to fully exploit these pathways." (PMID 30717356, 2019). "Given that FASN expression is commonly increased in virus‐associated cancers, lipogenesis appears to be essential for viral infection and cancer progression." (PMID 29968360, 2018). "It has been shown that viral infections can change subcellular localization of FASN; for example, Dengue infection causes FASN to relocalize to a perinuclear space, and Vaccinia virus infection relocalizes FASN to the mitochondria." (PMID 28962653, 2017). "In addition to the well-documented FASN upregulation associated with cancer and metabolic diseases, viral infections can also increase intracellular FASN levels, and many viruses require FASN activity to replicate." (PMID 40558086, 2025). "Interestingly, FASN inhibition can reduce both the number and size of lipid droplets induced by viral infection, demonstrating an association between FASN activity and the formation of lipid droplets during infection." (PMID 40558086, 2025). "Studies have shown that lipid metabolism is modulated upon virus infection, and that fatty acid synthase (FASN) is a key enzyme in fatty acid biosynthesis." (PMID 40131913, 2025). "Additional research should clarify the immunological outcomes when FASN is targeted in the context of viral infection." (PMID 40558086, 2025). "A subset of the FASN protein was found to be co-localized with the viral protein gD, providing a possibility to affect virus infection." (PMID 41196069, 2025). "The distribution profile of FASN proteins induced by viral infection appears similar to that of the Golgi apparatus, as we have previously reported." (PMID 41196069, 2025). "In the context of viral infection, siRNA1, siRNA2, and siRNA3 still maintained their efficacy in knocking down FASN protein expression." (PMID 41196069, 2025). "Here, we found that fatty acid synthase (FASN) protein is potentially involved in virus infection both in vitro and in vivo." (PMID 41196069, 2025). "Quantitative analysis indicated that the Golgi accumulated FASN protein levels decreased to approximately 35.75%, following virus infection." (PMID 41196069, 2025). "Viral infections can significantly alter cellular lipid metabolism by modulating key rate-limiting enzymes, including fatty acid synthase (FASN), stearoyl-CoA desaturase 1 (SCD1), and acetyl-CoA carboxylase (ACC)." (PMID 40387378, 2025). "Compared to the scrambled siRNA control, FASN protein levels were reduced to approximately 43.60%, 55.43%, and 75.43% by these three individual siRNAs, respectively, in the context of virus infection." (PMID 41196069, 2025). "Immunohistochemistry (IHC) was employed to evaluate the changes in FASN protein expression in response to viral infection in these TG neurons." (PMID 41196069, 2025). "Even after treatment with C75, which can also affect CPT1 activity, EV-A71 infection was reduced, suggesting that de novo fatty acid synthesis from FASN activity is essential for productive viral infection." (PMID 40558086, 2025). "The subsequent confirmation of these results via enzymatic activity assays reinforces the conclusion that FASN is actively induced as part of the viral infection process." (PMID 40327680, 2025). "According to the role of fatty acid metabolism in virus infection, the FASN gene is an interferon-regulated gene suppressed by IFN type I after infection by several viruses, including SARS-CoV-2." (PMID 38106410, 2023).
viral infection (continued). "Nevertheless, these observations cannot exclude the possibility that increased AMPK activity inhibits the expression of SCD1 and FASN through a similar mechanism to temporarily limit viral infection after ZIKV infection." (PMID 36405969, 2022). "The inhibition of FASN can suppress cell–cell membrane fusion and syncytia formation driven by viral proteins, impacting viral infection at multiple stages of the viral life cycle." (PMID 35631059, 2022). "Given that BoAHV-1 productive infection in Neuro-2A cells affects FASN protein expression, we further investigated whether FASN also plays a role in viral infection in the neural cell line using FASN knockdown and chemical inhibition." (PMID 41196069, 2025). "The viral infection-induced depletion of FASN was also observed in Neuro-2A cells." (PMID 41196069, 2025). "As FASN is important for immune activation (for review, see reference 104), future studies should elucidate if an immune response occurs upon FASN inhibition to support the clearing of viral infections." (PMID 40558086, 2025). "Thus, using two independent methods, we demonstrated that a portion of FASN protein localizes in the Golgi apparatus, and its content is reduced following viral infection." (PMID 41196069, 2025). "It seems that the localization of FASN to viral replication sites or replication complexes may represent a mechanism to facilitate virus infection observed in several viruses." (PMID 41196069, 2025). "Interestingly, IFN-I can significantly downregulate the expression of FASN, thereby reducing viral infection, which reveals a novel mechanism for the antiviral activity of IFN-I, namely the downregulation of metabolic gene expression." (PMID 38272906, 2024). "Inhibition of FASN is another strategy to treat viral infection." (PMID 38257735, 2023). "Hence, targeting FASN for inhibition can be a potential strategy to treat viral infection, especially enveloped viruses, which are more dependent on lipids." (PMID 38257735, 2023). "It is intriguing whether enhanced FASN palmitoylation could be a missing link in the molecular mechanism of virus infection and serve as a promising therapeutic target." (PMID 34803494, 2021). "How could FASN activity and subsequent de novo fatty acid production affect viral infection?" (PMID 40558086, 2025). "Thus, malonyl-CoA buildup due to FASN inhibition might be a toxic trait for cancer cells only; however, the effects of malonyl-CoA buildup during viral infection remain unknown." (PMID 40558086, 2025). "Therefore, FASN may play a crucial role in viral trafficking out of the Golgi apparatus, which could significantly expand our understanding of its role in viral infections within the virology community." (PMID 41196069, 2025). "This indicates that FASN may play a role in the viral infection process." (PMID 41196069, 2025). "FASN mRNA levels increased approximately 2.25-fold in MDBK cells and 1.90-fold in Neuro-2A cells following virus infection for 24 h, relative to mock-infected controls." (PMID 41196069, 2025). "CVB3-infected cells with the FASN inhibitor, cerulenin, resulted in a decrease in CVB3 viral yield, supporting previous reports that FASN is required for virus infection." (PMID 38953667, 2024). "The RT-qPCR and immunoblotting indicated that viral infection upregulated lipid synthesis enzymes, such as HMGCR, SREBP2, FASN, and ACC." (PMID 38989466, 2024). "Acetyl CoA carboxylase 1 (ACC1) and fatty acid synthase (FASN) are key nodes in the de novo fatty acid synthesis pathway simultaneously with the lipid metabolism pathway and is crucial against viral infection." (PMID 35215774, 2022). "Further, TVB-3166 inhibited viral infection at a dose of 0.07 μM, similar to its IC50 in an in vitro assay utilizing partially purified FASN (0.05 μM)." (PMID 26659560, 2015).